KRAS (KRas proto-oncogene, GTPase)
Diseases named in the same sentence as KRAS in open-access papers (continued):
Sharing a sentence is not in itself a finding about the gene and the disease.
lung cancer (continued). "The bioluminescence imaging and micro-CT results demonstrated that inhibition of HOXC10 significantly reduced bone metastasis of KRAS-mutant lung cancer in vivo." (PMID 39191757, 2024). "The data showed that iRGD-engineered exosomes specifically delivered KRAS siRNA to lung cancer cells following intravenous administration." (PMID 39355533, 2024). "Specifically, LKB1/KRAS transgenic animal models serve as translatable models for human lung cancer due to the similar molecular and histological characteristics of the tumors." (PMID 39763604, 2024). "For example, mutant KRAS in lung cancer can be significantly inhibited by targeting the land cycle to promote the accumulation of lipid metabolism prone to intracellular oxidation." (PMID 39309439, 2024). "Collectively, these findings highlight the relationship between KRAS mutation, MYC deregulation and PD-L1 overexpression, making them promising targets for lung cancer immunotherapy." (PMID 39164274, 2024). "We observed similar findings in additional in vitro models of KRAS-mutant pancreatic and lung cancers." (PMID 38822082, 2024). "A subset of patients with KRAS-mutant lung cancer has greatly benefited from the advent of ICB therapy." (PMID 38635884, 2024). "This case highlights several key aspects in treating BRG-1-deficient lung cancer: the impact of partial BRG-1 deletion, the potential role of immunotherapy, the effects of concurrent KRAS G12C mutation, and the importance of comprehensive molecular analysis." (PMID 39777351, 2024). "In vivo CRISPR–Cas9 screening in an immunogenic murine lung cancer model identified mechanisms by which oncogenic KRAS promotes immune evasion, most notably via upregulation of immunosuppressive COX2 in cancer cells." (PMID 38635884, 2024). "Our experiments showed that HOXC10 inhibition impeded the proliferation and migration of KRAS-mutant lung cancer cells in vitro and attenuated osteolytic bone metastasis in vivo." (PMID 39191757, 2024). "A study investigating apigenin as an anticarcinogenic agent in KRAS-mutant lung cancer cells revealed its ability to inhibit MUC1-C and PD-L1 expression, accompanied by the downregulation of STAT3 expression." (PMID 39690423, 2024). "In this study, we found that IL6/STAT3 pathway confers resistance to HOXC10 inhibition in KRAS-mutant lung cancer bone metastasis and that activation of p-STAT3Tyr705 further promotes cell survival after HOXC10 inhibition." (PMID 39191757, 2024). "KRAS G12C mutations have been identified in metaplastic epithelium in honeycomb foci, highlighting the plausible common pathogenetic pathway of IPF and lung cancer." (PMID 39062713, 2024). "Mutant KRAS promotes FAO through acyl-coenzyme A (CoA) synthetase long-chain family member 3 (ACSL3) in lung cancer cells in an ACSL3-dependent manner." (PMID 38841622, 2024). "This will help inform the combination use of FDA-approved MEK inhibitors and STAT3 inhibitor in an ongoing phase I clinical trials (ClinicalTrials.gov ID:NCT03195699) to treat with KRAS-mutant lung cancer bone metastasis patients." (PMID 39191757, 2024). "Research has shown that mutant KRAS lung cancer relies on newly synthesized fatty acids to evade ferroptosis, presenting a targetable vulnerability." (PMID 38495496, 2024). "This case report explores a case of mixed lung cancer with partial BRG-1 deficiency and KRAS G12C mutation, highlighting its clinical relevance, treatment challenges, and the importance of comprehensive molecular profiling." (PMID 39777351, 2024). "Genetic or pharmacological inhibition of FAK leads to reduced proliferation and increased cell death in KRAS mutant lung cancer cells, while sparing cells carrying wild-type KRAS." (PMID 39271958, 2024). "In a lung cancer setting, a mouse model of KRAS-induced lung adenocarcinoma and KRAS and CD44 expression were evaluated to determine the in vivo role of CD44 related to KRAS." (PMID 38672650, 2024).
lung cancer (continued). "Targeting of CTLA-4 together with MEK, using trametinib or selumetinib, resulted in increased survival in KRAS-mutant lung cancer mouse models." (PMID 38731852, 2024). "Taken together, these findings reveal that HOXC10 effectively alleviates pan-KRAS-mutant lung cancer with bone metastasis in the NOD1/ERK axis-dependent manner, and support further development of an effective combinatorial strategy for this kind of disease." (PMID 39191757, 2024). "The oncogene Myc acts as a transcriptional suppressor of type I IFN response genes in pancreatic cancer, and we have recently shown that Myc mediates KRAS-driven inhibition of IFN response genes in lung cancer." (PMID 38635884, 2024). "Co-alterations in KRAS plus LKB1 are frequent in lung cancer, and patients with these alterations are reported to display resistance to current therapeutic options such as chemotherapy and/or immunotherapy." (PMID 39213022, 2024). "Conversely, in a KRAS-driven lung cancer model, long-term supplementation with NAC and vitamin E has been demonstrated to promote metastasis and has been attributed to the stabilization of BACH1 and a metabolic shift in invasive cancer cells." (PMID 38247494, 2024). "Clinical trials involving the KRAS G12C inhibitors sotorasib and adagrasib demonstrated modest response rates and PFS in lung cancer patients carrying this mutation (28% and 43%, and 5.6 months and 6.5 months, respectively)." (PMID 38612902, 2024). "provided the latest advances in anti-KRAS therapy for lung cancer, as well as mechanistic insights into biodiversity and potential clinical significance." (PMID 38706597, 2024). "KRAS is a kind of GTPase protein, firstly found on chromosome 12 of human lung cancer cells in 1982." (PMID 38872211, 2024). "In KRAS mutant lung cancer cells, the cooperative actions of LKB1 and NRF2 drive metabolic reprogramming and induce a reliance on glutamine." (PMID 38247494, 2024). "Lung cancer EVs contain several tumor-associated proteins, such as EGFR, KRAS, inducer of extracellular matrix metalloproteinase, claudins, and RAB family proteins." (PMID 38893088, 2024). "IL6/STAT3 pathway is activated in KRAS-driven tumors and can contribute to tumor occurrence and drug resistance in lung cancer." (PMID 39191757, 2024). "We propose a regimen of dual inhibition of HOXC10 and STAT3 for improving the effectiveness of HOXC10 inhibition alone in KRAS-mutant lung cancer bone metastasis." (PMID 39191757, 2024). "Despite advances in diagnosis and treatment, the overall prognosis for patients with KRAS-driven lung cancer remains poor, underscoring the urgent need for a deeper understanding of the underlying molecular mechanisms." (PMID 39485842, 2024). "The importance of autophagy in the initiation and/or progression of KRAS- or BRAF-driven lung cancer was revealed through analysis of GEM models in which deletion of key autophagy genes (Atg5 or Atg7) accompanied the initiation of oncoprotein expression." (PMID 39213022, 2024).
lung cancer (continued). "Among those aged ≥40 years, who accounted for 88.4% of the total number of people with disabilities, the top three most frequently used tests were colorectal and lung cancer‐related (KRAS, NRAS, and EGFR)." (PMID 38711356, 2024). "We calculated the half inhibitory concentration (IC50) of DDD85646 on EGFR mutant (H1975 and H1650) and KRAS/EGFR wild-type lung carcinoma cells (H1299 and H522) at 72 hours of treatment." (PMID 38949950, 2024). "Our data suggest that NMT1 is a potential therapeutic target in lung carcinomas with mutant KRAS and LKB1 and/or KEAP1 (KL/K)MUT, which are highly aggressive and resistant to current therapies, including immune checkpoint inhibitors." (PMID 38949950, 2024). "We report that NMTs are a novel therapeutic target in lung carcinoma cells with LKB1 and/or KEAP1 mutations in a KRAS-mutant background." (PMID 38949950, 2024). "We show that NMTis are effective as single agents against lung carcinomas with concurrent LKB1 and/or KEAP1 mutations in a KRAS-mutant background (KL/K)MUT and sensitize cells with these mutations to platinum-based chemotherapy." (PMID 38949950, 2024). "Common genetic mutations in lung carcinoma include EGFR, KRAS, EML4-ALK, Ros1, and c-MET, among others." (PMID 38571504, 2024). "On the other hand, a recent study demonstrated that knocking out EGRF in a mouse model of KRAS-G12D-mutant lung cancer resulted in tumor regression, although compensation by a non-ERBB family was seen in the later stage of the disease." (PMID 36899885, 2023). "An elegant study demonstrated that anti-estrogen fulvestrant and pan-HER inhibitor (dacomitinib) reduced the oncogenic interplay between ER and RTKs (EGFR) to exert synergistic anti-tumor effects in mouse models of KRAS mutant lung cancer." (PMID 37686465, 2023). "A study found that the sequential triple therapy of anti-PD-1 ICIs sequentially after fulvestrant (anti-estrogen) plus dacomitinib (a pan-HER inhibitor) had the potential for treating KRAS-mutant lung cancer." (PMID 36675641, 2023). "M Morita used KRAS in PKM2 mutant lung cancer mouse models (KrasG12D or KrasG12V) and in SCLC cells." (PMID 37190124, 2023). "Numerous studies have demonstrated the importance of Tregs in preclinical models of KRAS-mutant lung cancer as depletion of these immunosuppressive cells stimulates antitumor immunity and reduces tumor growth." (PMID 37581538, 2023). "This led to the identification of a set of 16 TSGs whose high expression correlated with an improved overall survival in KRAS mutant lung cancer patients." (PMID 37407562, 2023). "The combination of trametinib and CDK4/6 inhibitors in KRAS-mutated solid tumors, including PDAC, lung cancer, and colorectal cancer, also elicited a robust therapeutic response." (PMID 37817078, 2023). "It was found that wild type (WT) HRAS and NRAS have a crucial role in the activation of ATR/CHK1-mediated DDR, which leads to genomic instability in KRAS-mutant lung cancer cells." (PMID 36899885, 2023). "For example, a study reported that autophagy inhibition enhanced sensitivity to ferroptosis in pancreatic cancer cells, while a study showed that autophagy inhibition promoted ferroptosis-induced cell death in KRAS-mutant lung cancer cells." (PMID 37491375, 2023). "Treatment of lung cancer cells with inhibitors of KRAS, EGFR or ALK results in caspase-3-regulated activation of GSDME, thereby increasing the anticancer efficacy of these drugs." (PMID 36920176, 2023). "RT-qPCR analysis also detected higher expression of HIF1A-As2 in five of seven KRAS mutant lung cancers compared to matched normal lungs from MCRC Biobank LUAD TMAs samples." (PMID 37041291, 2023). "Silencing CPS1 in KRAS/LKB1-mutant lung cancer cells has been found to lead to pyrimidine depletion, S-phase progression, DNA-polymerase stalling, DNA damage, and cell death." (PMID 36983664, 2023).
lung cancer (continued). "In LUAD patients and KRAS mutant lung cancer mice, the mutant KRAS activated PI3K/STAT3 signal transduction, thus inhibiting the post-transcriptional inhibition of CD47 by miR-34a." (PMID 37670322, 2023). "To further prove the presence of enhancer activity at mouse Etv1 intron 4, we cloned the DNA fragment from the ATAC-Seq peak region into a luciferase reporter construct that was subsequently transfected into A549, a human KRAS mutant lung cancer cell line." (PMID 36810256, 2023). "The inhibition of IL-6 in KRAS-mutant lung cancer mouse models revealed lower pro-tumor characteristics in the TME, leading to tumor suppression." (PMID 36899885, 2023). "In conclusion, the targets for KRAS‐positive lung cancer that can be detected in blood and tissue samples differ." (PMID 37751775, 2023). "Next, we sought to assess the effect of TGFβ inhibition on SHP099-induced migration and invasion in KRAS mutant lung cancer models." (PMID 38102334, 2023). "Further screening of the strongest genetic interactions in nine lung cancer cell lines uncovered a robust KRAS-dependent interaction between RHOA and RAP1GDS1, a GEF for RHO family GTPases." (PMID 36607281, 2023). "EZH2 was highly expressed in lung cancers with positive KRAS expression, and the correlation was significant in lung adenocarcinoma (r = 0.3129, p < 0.001)." (PMID 37069494, 2023). "LKB1−/− KRAS lung cancer is one of the most aggressive subtypes of lung cancer and responds poorly to ICIs." (PMID 38106674, 2023). "We created dose–effect curves to determine the IC50 concentration of sotorasib, and IC10 of metformin in three lung cancer cell lines; A549 (KRAS G12S), H522 (wild-type KRAS), and H23 (KRAS G12C)." (PMID 36901764, 2023). "KRAS codon 12 (G12C) is one of the recently approved biomarkers for targeted therapy in lung cancer." (PMID 36994199, 2023). "Non-small cell lung cancer (NSCLC) is the most common lung cancer diagnosis, among which epidermal growth factor receptor (EGFR), Kirsten rat sarcoma (KRAS), and anaplastic lymphoma kinase (ALK) mutations are the common genetic drivers." (PMID 36949948, 2023). "These dysregulated miRNAs also interact with various signaling pathways that are frequently mutated in lung cancer, such as the EGFR and KRAS pathways, further highlighting their roles in the disease." (PMID 37631277, 2023). "Last year, the FDA granted accelerated approval for sotorasib, the first KRAS‐blocking drug for patients with non‐small cell lung cancer (NSCLC)." (PMID 36670542, 2023). "Both in vitro and in vivo studies demonstrated the KRAS-disrupting ability of this nanoparticle in lung cancer." (PMID 38258073, 2023). "Two human KRAS-G12C-positive lung cancer cell lines, Calu1 and H2030, were similarly submitted to growth assays with combinations of MRTX-1257 and RMC-4550." (PMID 36845684, 2023). "It has been demonstrated in experimental mouse models that COPD-like airway inflammation can lead to lung cancer promotion in a context of KRAS mutant epithelial cells." (PMID 37838700, 2023). "ERK3 promotes migration and invasion and tumorigenesis of lung cancer cells expressing either wild-type KRAS (e.g., H1299) or mutants (e.g., A549 and H23)." (PMID 37287450, 2023). "KRAS-G12D mutation reduced PD-L1 expression through P70S6K/PI3K/AKT pathway and decreased CXCL10/CXCL11 expression via inhibition of HMGA2 in lung cancer cells." (PMID 36874015, 2023). "We evaluated the radiosensitivity effect of KZ-001 in 2 KRAS-mutant lung cancer cell lines A549 (KRAS G12S) and H460 (KRAS Q61H)." (PMID 37899758, 2023). "More recently, our group has shown that the combined blockade of Id1 and PD-1/PD-L1 displays synergistic therapeutic activity in KRAS-mutant lung cancer in mouse models." (PMID 37841258, 2023).
lung cancer (continued). "In lung cancer, it can significantly inhibit the proliferation of KRAS mutant lung cancer, downregulate the expression of programmed death-ligand 1 induced by interferon-gamma, and reduce the migration of Lewis lung cancer cells in a CCL2-dependent manner." (PMID 37716981, 2023). "In primary lung cancer, a retrospective study found KRAS-mutant tumors had a significantly higher PD-L1 expression, high CD8+T cells infiltration and higher TMB than EGFR-mutant tumors." (PMID 37065830, 2023). "Small molecules targeting HIF1A-As2 and MYC significantly inhibit tumor growth, suggesting lncRNA HIF1A-As2 presents an important biological and clinical impact in lung cancer, particularly in KRAS-driven NSCLC." (PMID 37041291, 2023). "Other interesting novel combination involves bevacizumab (anti-VEGF) since this therapy was shown to be inactive in KRAS mutant lung cancer." (PMID 38239281, 2023). "Later, the same research team demonstrated that NAC and vitamin E promote lung cancer metastasis in mice, in which Cre-adenovirus administration activates KRAS overexpression." (PMID 37009472, 2023). "In our study, EZH2 was highly expressed in lung cancers with positive KRAS expression, and the correlation was significant in lung adenocarcinoma (r = 0.3129 and p < 0.001)." (PMID 37069494, 2023). "In summary, we demonstrate that it is highly feasible to utilise frozen EBUS-TBNA in patients with advanced lung cancer to quantify TMB and other putative immunotherapy biomarkers including PD-L1 copy number and KRAS mutation status." (PMID 36994206, 2023). "B(a)P is one of the well-studied tobacco-specific carcinogen, it induces mouse lung tumors develop key KRAS mutations [G12C (56%), G12V (25%) and G12D (19%)] similar to those observed in mutant KRAS human lung cancer." (PMID 37520581, 2023). "Here, we developed multiple models of acquired resistance to dual-mechanism ERK/MAPK inhibitors across KRAS-mutant pancreatic, colorectal, and lung cancers, and then probed the long-term events enabling survival against this class of drugs." (PMID 37961649, 2023). "With the advent of treatment methods, it has become clinically important to identify KRAS‐positive lung cancers, especially KRAS G12C‐positive lung cancers." (PMID 37751775, 2023). "KRAS mutant lung adenocarcinoma is the most frequent molecular subtype of lung cancer but it is still a heterogenous entity since the individual allelic variants are biologically heterogenous." (PMID 38239281, 2023). "For instance, PTEN is rarely mutated in KRAS- and BRAF-driven human lung cancers, and yet Pten inactivation provides a very strong tumor fitness advantage in our autochthonous mouse models." (PMID 37828026, 2023). "In the past decade target therapy changed the treatment of lung adenocarcinoma which left KRAS mutant lung cancer in an orphan status which changed recently significantly." (PMID 38239281, 2023). "Mitochondrial respiration was also found to be essential for tumorigenesis in a KRAS-driven mouse model of lung cancer through the generation of ROS, which were required for the MAPK signaling-dependent induction of anchorage-independent growth." (PMID 37190033, 2023). "In another study let-7g efficiently encourages cell cycle detention and cell death in K-RasG12D expressing murine lung cancer cells by targeting KRAS oncogene." (PMID 37813634, 2023). "To identify genes specifically required for KRAS-driven oncogenesis in primary cancer spheroids, we performed a parallel screen using a mouse lung cancer cell line (LKR10), previously derived from the Kras G12D mouse model, cultured in standard 2D conditions." (PMID 37407562, 2023). "Exposure to polycyclic aromatic hydrocarbons contained in CS can induce glycine to tyrosine KRAS transversions in lung cancer." (PMID 37511536, 2023).